SCN2A (sodium voltage-gated channel alpha subunit 2)
Diseases named in the same sentence as SCN2A in open-access papers (continued):
Sharing a sentence is not in itself a finding about the gene and the disease.
episodic ataxia (12 papers, 2018 to 2025). "For instance, the autosomal dominant SCN2A variant p.L1650P presented in a male child as episodic ataxia but in the father as episodic hemiplegia, two very distinct diagnoses." (PMID 39606727, 2024). "Pathogenic variants in at least 21 patients with SCN2A-associated episodic ataxia were recently reported, including our Case-2 (p.Val1325Phe), with age of onset ranging from early infancy (10 months) to adolescent onset (14 years) and with wide phenotypic variation." (PMID 32466254, 2020). "While the SCN2A variant is likely to be causal for episodic ataxia, each variant may potentially contribute to the phenotypes observed in this family." (PMID 30314295, 2018). "With our report, three major neuronal voltage-gated sodium channel genes (SCN1A, SCN2A, and SCN8A) have now been implicated as causative genes of episodic ataxia." (PMID 38251463, 2023). "In SCN2A, episodic ataxia has been described in 21 individuals, with a third affected by the recurring gain-of-function variant A263V." (PMID 38251463, 2023). "An important exception is represented by SCN2A cases, in which BFIS are accompanied by no or mild DD, seizure freedom since infancy, and are followed by the development of childhood-onset episodic ataxia." (PMID 33919646, 2021).
West syndrome (11 papers, 2015 to 2025). "The Patient 48 was diagnosed with intractable West syndrome, recurrent SCN2A variation R853Q was detected." (PMID 35431799, 2022).
Anxiety (9 papers, 2019 to 2025). Intense feelings of nervousness, tension, or panic often arise in response to interpersonal stresses. "Young Scn2a mutants demonstrated lower anxiety levels in EPM and OFT, as well as reduced immobility during the TST, in contrast to adult mutants." (PMID 41585885, 2025). "Scn1a mutants, Gabrb3+/N328D knock-in mice, and young Scn2a mutant mice were also revealed to exhibit normal anxiety levels in several paradigms." (PMID 41585885, 2025). "In the open-field test, Scn2a+/- mice showed normal levels of locomotor activity and time spent in the center of the open-field arena (a measure of anxiety-like behavior) compared with WT mice." (PMID 31249508, 2019). "The Scn2a model revealed a clear developmental contrast in anxiety phenotypes." (PMID 41585885, 2025). "Additionally, deletion of Scn2a in the mPFC was found to increase social interaction and anxiety-like behaviors but decrease locomotion when compared to control-treated animals; this effect was not seen when Scn2a was deleted in the VTA." (PMID 39606727, 2024). "Based on DisgeNet data, Acsl4, Clock, Scn2a, and Hivep2 are confirmed as anxiety-related genes." (PMID 36979479, 2023). "We next assessed whether conditional deletion of Scn2a in excitatory or inhibitory neurons had an impact on anxiety-like behavior in the elevated-plus maze task." (PMID 30962870, 2019). "Scn2a+/- mice were then subjected to tests measuring anxiety-like behaviors." (PMID 31249508, 2019). "Consequently, reduced signaling from the amygdala may attenuate HPA activity during stress, explaining the lower anxiety phenotypes observed in young Scn2a mutants." (PMID 41585885, 2025). "The Scn2a ASO mice displayed reduced sociability and increased hyperactivity and anxiety-like behaviors." (PMID 39606727, 2024). "Having established social disinhibition and decreased anxiety (on the EPM) as phenotypes associated with decreased Scn2a expression, analysis of circuit deficits in WS may serve as a guide for future studies to investigate the consequences of Scn2a haploinsufficiency." (PMID 34156984, 2021). "Because anxiety and depression are among the most frequently diagnosed comorbidities in patients with ASD34, we assessed anxiety- and depression-related behavior in Scn2a+/− mice." (PMID 31501495, 2019). "In addition, Scn2a+/- mice show suppressed hippocampal long-term potentiation (LTP) in association with impaired spatial learning and memory, but show largely normal locomotor activity, anxiety-like behavior, social interaction, repetitive behavior, and whole-brain excitation." (PMID 31249508, 2019). "Lastly, Scn2a+/- mice showed no anxiety-like behavior, as measured by the time spent in the center region of the open-field arena." (PMID 31249508, 2019).
Ataxia (9 papers, 2012 to 2025). Ataxia refers to impaired coordination of voluntary muscle movement. "Brain sodium channelopathies, which include mutations in SCN1A, SCN2A, SCN3A, and some mutations in SCN8A observed in cases of familial human ataxia and in mice models of ataxia and end-plate diseases (these genes encode the channels NaV1.1, NaV1.2, β1-subunit, and NaV1.6 respectively)." (PMID 22798951, 2012). "Of these, 3 variants (p.Val1325Phe in SCN2A, p.Arg756His in ATP1A3, and p.Arg167Met in KCNA1) overlap with those identified from the analysis of the ataxia-related genes identified in Tier-1." (PMID 32466254, 2020).
Cognitive impairment (7 papers, 2019 to 2025). Abnormal cognition is characterized by deficits in thinking, reasoning, or remembering. "The autistic-like behaviors and comorbid cognitive deficits that we observed in Scn2a+/− mice during the juvenile/adolescent period of development are therefore consistent with the symptoms described in these young patients." (PMID 31501495, 2019). "We therefore evaluated the presence of cognitive deficits in young and adult Scn2a+/− mice using different memory tests." (PMID 31501495, 2019). "Severe cognitive impairment occurred in patients with mutations in NKX6-2, PLP1, PAH gene (when untreated), and SCN2A (in early-onset type), whereas milder ID was associated with SCN2A (in late-onset type) or SMAD6 variants." (PMID 41300846, 2025). "Despite the association between LOF mutations in SCN2A, FMR1, and CDKL5 and ASD with ID, shared mechanisms underlying cognitive impairments remain unknown." (PMID 40053578, 2025). "Autistic individuals with LoF variants in the four moderate-risk genes (NAV3, ITSN1, SCAF1 and HNRNPUL2; n = 95) have less cognitive impairment than 129 autistic individuals with LoF variants in highly penetrant genes (CHD8, SCN2A, ADNP, FOXP1 and SHANK3) (59% vs 88%, P = 1.9 × 10−6)." (PMID 35982159, 2022). "In addition to lower reactivity to stressful stimuli, young Scn2a+/− mice display cognitive deficits as evidenced by altered mnesic functions." (PMID 31501495, 2019).
Dystonia (5 papers, 2015 to 2024). An abnormally increased muscular tone that causes fixed abnormal postures. "Since it is already known that single gene disorders, including SCN1A, SCN2A, KCNQ2, PRRT2, and pyridoxine deficiency, can result in isolated dystonia, we add CdLS5 (HDAC8 variation) to this expanding spectrum." (PMID 38910710, 2024). "It is already known that single gene disorders, including SCN1A, SCN2A, KCNQ2, PRRT2, and pyridoxine deficiency, can result in isolated dystonia; we add CdLS5 (HDAC8 variation) to this expanding spectrum." (PMID 38910710, 2024).
generalized epilepsy (4 papers, 2015 to 2024). Epilepsy that is characterized by generalized seizure types and may have typical interictal and/or ictal EEG findings that accompany generalized seizure types (for example generalized spike-wave). "Likewise, mutations in the SCN2A gene (A467T), that encodes the voltage-gated sodium channel Nav1.2, have been shown to elicit seizure behavior such as in generalized epilepsy with febrile seizure plus (GEFS+) syndrome by also enhancing sodium currents." (PMID 39253727, 2024). "Similarly, mutations in NaV1.2 (SCN2A) and NaVβ1 (SCN1B) can lead to generalized epilepsies." (PMID 31933626, 2019).
infantile epilepsy (4 papers, 2017 to 2024). "Patients with GOF variants in SCN2A (i.e., onset before three months) and SCN8A (i.e., onset in the first year) present early with infantile epilepsy with variable severities, while those with LOF variants present later in childhood." (PMID 38540325, 2024).
scrapie (4 papers, 2011 to 2018). A fatal disease of the nervous system in sheep and goats, characterized by pruritus, debility, and locomotor incoordination. "In the current study, qualitative and quantitative lipid analyses by HPLC-MS revealed multiple anomalies associated with prion infection both in ScN2a cell cultures and scrapie-affected C57Bl/6 mouse brains, mainly consisting in abnormal accumulation of CE." (PMID 21816038, 2011). "We also examined the efficacy of anti-prion activity of BBG using neuronal derivative N2a cells infected with the Chandler murine strain of scrapie (ScN2a)." (PMID 22693582, 2012). "The HPLC-MS data also allowed us to show that, compared to normal brains, CE/CT percentages significantly increased (p = 0.029) in brains of the scrapie-affected mouse group (from 9.2% to 12.3%), while they did not vary in N2a and ScN2a cells (27.0% vs. 26.8%, respectively)." (PMID 21816038, 2011).
dementia (3 papers, 2015 to 2025). Loss of intellectual abilities interfering with an individual's social and occupational functions. "Thus, SCN2A is associated with bipolar disorder and dementia." (PMID 39228919, 2024). "In conclusion, the genes CACNA1C, GABBR2, SCN2A, CTSH, MSRA, and SH3PXD2A may be associated with the neuro-progression of bipolar disorder to dementia." (PMID 39228919, 2024). "In conclusion, CACNA1C, GABBR2, SCN2A, CTSH, MSRA, and SH3PXD2A may be associated with the neuro-progression of bipolar disorder to dementia." (PMID 39228919, 2024). "According to GWAS, the CACNA1C, GABBR2, SCN2A, CTSH, MSRA, and SH3PXD2A genes were common between bipolar disorder and dementia." (PMID 39228919, 2024). "The results showed that the genes CACNA1C, GABBR2, SCN2A, CTSH, MSRA, and SH3PXD2A were overlapping between patients with bipolar disorder and dementia." (PMID 39228919, 2024).
ovarian carcinoma (3 papers, 2015 to 2024). A malignant neoplasm originating from the surface ovarian epithelium. "The prognostic information of our five hub genes were determined using the KM plotter (SCN2A, ELAVL2, BCL2, MAF, and ZNF532,) to confirm the association between patterns of expression and metastasis risk in ovarian cancer patients." (PMID 38654363, 2024). "The previous study observed a downregulation of the genes SCN2A, ELAVL2, ZNF532, MAF and BCL2 which were identified in ovarian cancer." (PMID 38654363, 2024).
sleep disorder (3 papers, 2022 to 2024). A change from the patient's baseline sleeping pattern, in the hours slept and/or an alteration/dysfunction in the stages of sleep. "Improving the understanding of Nav1.2’s role in sleep can enhance the treatment of SCN2A-related sleep disorders by identifying affected sleep cycles and mechanisms, leading to more precise treatment targets." (PMID 39606727, 2024). "This gene is homologous with human genes SCN1A, SCN2A and SCN3A, which encode sodium channels and have been associated with neuronal and sleep disorders." (PMID 35189951, 2022).
temporal lobe epilepsy (3 papers, 2014 to 2025). A localization-related (focal) form of epilepsy characterized by recurrent seizures that arise from foci within the temporal lobe, most commonly from its mesial aspect. "The differential expression of SCN2A was assessed in the cerebral cortex of patients with primary and secondary temporal lobe epilepsy and normal brain cortex tissue." (PMID 24220630, 2014). "The result suggested that the low expression of SCN2A in the cerebral cortexes of patients with primary and secondary temporal lobe epilepsy induced the repeated discharge." (PMID 24220630, 2014). "In the present study, in terms of RNA levels and protein levels, normal brain cortex tissues exhibited a higher expression of SCN2A than the cerebral cortexes of patients with primary or secondary temporal lobe epilepsy." (PMID 24220630, 2014). "The results indicated that there is a low expression of SCN2A and Cu-Zn SOD in the epileptic cerebral cortex and provided novel insights into potential therapies for temporal lobe epilepsy." (PMID 24220630, 2014). "SCN2A expression and the concentration of Cu-Zn SOD in the cerebral cortexes of patients with primary and secondary temporal lobe epilepsy and normal brain cortex tissues were detected." (PMID 24220630, 2014). "In addition, co-transfection with the si-SCN2A vector and the overexpressed Cu-Zn SOD vector was performed in order to illustrate the effect of Cu-Zn SOD vector therapy on temporal lobe epilepsy." (PMID 24220630, 2014).
Alpers syndrome (2 papers, 2021 to 2023). A cerebral degeneration that results in progressive degeneration of grey matter in the cerebrum and has_symptom convulsions. "Our retrospective data analysis shows an initial response to KD in 50% of patients, even in etiologies known to be severe and drug resistant (Alpers syndrome, SCN2A mutation)." (PMID 34149600, 2021). "Third, our series has an overrepresentation of children with severe underlying disease (Alpers syndrome, SCN2A), in half of the patients leading to death or poor neurological long-term outcome." (PMID 34149600, 2021). "Of these patients, two had a diagnosis of Alpers syndrome (patients 3 and 7), one of SCN2A mutation (patient 5), and one of unknown etiology (patient 2)." (PMID 34149600, 2021). "Genetic testing revealed Alpers syndrome with POLG mutation in 3 (37.5%) patients and a SCN2A-mutation in 1 (12.5%) patient." (PMID 34149600, 2021).
episodic ataxia, type 9 (2 papers, 2021). "Episodic ataxia type 9 (EA9) is caused by pathogenic variants in SCN2A, which encodes the α-subunit of the voltage-gated sodium channel NaV1.2." (PMID 34566847, 2021).
Lennox-Gastaut syndrome (2 papers, 2021 to 2022). Lennox-Gastaut syndrome (LGS) belongs to the group of severe childhood epileptic encephalopathies. "Mutations in SCN2A and SCN8A, the genes that encode NaV1.2 and NaV1.6, respectively, have been implicated in Lennox-Gastaut syndrome (LGS), another severe childhood epilepsy (Epi4K." (PMID 35689251, 2022).
polymicrogyria (2 papers, 2022 to 2023). A developmental brain abnormality characterized by an excessive amount of small convolutions on the surface of the brain and cognitive dysfunction. "SCN2A was recently reported as potentially associated with polymicrogyria, and our findings solidify this association." (PMID 37486637, 2023). "In addition to detecting pathogenic variants in genes previously linked to polymicrogyria (eg, ADGRG1/GPR56, SCN3A, TUBB2B), we discovered 6 genes linked to polymicrogyria for the first time (QRICH1, TMEM161B, PANX1, KIF26A, SCN2A, and MAN2C1)." (PMID 37486637, 2023).
Tourette syndrome (2 papers, 2018 to 2021). A neurologic disorder caused by defective metabolism of the neurotransmitters in the brain. "We discuss the association of SCN2A, SCN3A, GRB14, COBLL1 and SCL38A11 deletions with ASD and Tourette syndrome and possible implications for treatment." (PMID 30071822, 2018). "To date, there is no previous description of a patient with comorbid ASD and Tourette syndrome showing a deletion containing SCN2A and SCN3A." (PMID 30071822, 2018).
arthropathy (1 paper, 2025). Any disorder of the joints. "We suggest testing patients who are negative for common disease‐causing variants in SeLFIE (SCN2A, SCN8A, KCNQ2, PRRT2) for the ANKH c.‐11C>T change, especially if there is evidence for a familial arthropathy." (PMID 40574727, 2025).
attention deficit-hyperactivity disorder (1 paper, 2019). A disorder characterized by a marked pattern of inattention and/or hyperactivity-impulsivity that is inconsistent with developmental level and clearly interferes with functioning in at least two settings (e.g. at home and at school). "Other hub genes (GABBR2, GRM7, MEF2C, SCN2A, KMT2C, and DAGLA) dysfunction have been reported to contribute to ASD and other psychiatric disorders such as Attention-Deficit Hyperactivity Disorder (ADHD), Huntington’s disease, and Rett-syndrome." (PMID 31649562, 2019).
cerebral palsy (1 paper, 2024). A group of disorders affecting the development of movement and posture, often accompanied by disturbances of sensation, perception, cognition, and behavior. "An 11-year-old girl was bedridden due to underlying medical conditions after visiting our pediatric department for an SCN2A abnormality, cerebral palsy, and intractable spasticity." (PMID 38966476, 2024).
congenital myopathy (1 paper, 2024). "We have reported undocumented phenotypic features associated with SCN2A and SCN4A variants and two novel variants linked to severe fetal congenital myopathy 22B." (PMID 38255008, 2024).
demyelinating disease (1 paper, 2025). A broad group of disorders that affect the myelin sheaths that cover the neurons. "Given the essential role of SCN2A in oligodendrocyte development, its dysregulation may have implications for demyelinating diseases or neurodevelopmental disorders associated with Nav1.2 dysfunction." (PMID 40806469, 2025).
Epileptic spasm (1 paper, 2022). A sudden flexion, extension, or mixed extension-flexion of predominantly proximal and truncal muscles that is usually more sustained than a myoclonic movement but not as sustained as a tonic seizure. "In this series, 8/36 patients (22.2%) had epileptic spasms, including those with KCNT1, SCN2A, SCN1A, DOCK6 and PCDH19 variants." (PMID 35715422, 2022).
Focal cortical dysplasia (1 paper, 2025). A type of malformation of cortical development that primarily affects areas of neocortex. "Additionally, cluster #2, which focuses on focal cortical dysplasia (FCD), also shows a high incidence, as not only mutations in SCN1A and SCN2A that lead to excessive neuronal excitation result in FCD, but mutations in genes encoding potassium channels can also produce similar outcomes." (PMID 40667464, 2025).
fragile X syndrome (1 paper, 2021). A genetic syndrome caused by mutations in the FMR1 gene which is responsible for the expression of the fragile X mental retardation 1 protein. "Defects with a large effect seen in syndromes such as the PMDS or fragile X syndrome, but also mutations affecting high confidence ASD risk genes such as SCN2A and CHD8 will represent primary targets of such new therapies." (PMID 34784886, 2021).
Hypertension (1 paper, 2017). The presence of chronic increased pressure in the systemic arterial system. "The sodium channels, voltage-gated alpha subunit gene SCN2A is considered as one candidate for hypertension detection." (PMID 27802793, 2017).
Hypsarrhythmia (1 paper, 2022). Hypsarrhythmia is abnormal interictal high amplitude waves and a background of irregular spikes. "Vitamin B6 allowed patients with ALDH7A1 and PNPO mutations to achieve seizure-free status, oxcarbazepine was effective for patients with SCN2A, ATP7A, WWOX, and PRRT2 mutations, and ACTH was partly effective for DOCK6 mutation patients with spasms and hypsarrhythmia." (PMID 35715422, 2022).
insomnia (1 paper, 2023). A sleep disorder characterized by difficulty in falling asleep and/or remaining asleep. "Tetradecanoic acid (Z-score = − 1.00) potentially affects several important proteins-associated with insomnia, including ADRB2, DRD2, and SCN2A." (PMID 37573423, 2023).
memory impairment (1 paper, 2025). "In contrast, young Scn2a mutant mice displayed age-dependent memory impairment which did not last till adulthood." (PMID 41585885, 2025).